CEACAM5 (CEA cell adhesion molecule 5)
Diseases named in the same sentence as CEACAM5 in open-access papers (continued):
Sharing a sentence is not in itself a finding about the gene and the disease.
tumor (continued). "To validate our CEACAM5 observations, we used batch-corrected RNA-seq data derived from The Cancer Genome Atlas (TCGA) Pan-Cancer Initiative11 from normal tissue, primary tumor tissue, and metastatic or recurrent tumor tissue." (PMID 33004987, 2020). "It has been analyzed in a previous publication and been shown to add clinical information over analysis of CEACAM5 identifying tumor cells that are particularly aggressive." (PMID 32049988, 2020). "KLK6 mRNA was chosen because it is ectopically expressed in CRC tumor in contrast to CEACAM5 and MUC2 that are expressed at similar levels in CRC tumors and normal colon." (PMID 32049988, 2020). "During tumor progression, CEACAM5 is shed off the tumor cell surface and can be detected in the serum, where it is a clinically reliable marker for CRC diagnosis." (PMID 31447859, 2019). "Taken together, these results suggest that CEACAM5 promotes MET to facilitate tumor outgrowth at metastatic sites." (PMID 29736411, 2018). "Conversely, the clear majority of the 10 most abundant human-derived gene products detected exclusively in tumor parenchyma (e.g., CEACAM5, MUC5B, FCGBP) were found to be involved in metastasis." (PMID 29899869, 2018). "CEACAM5, the carcinoembryonic antigen, was originally detected in the search for tumor-specific antigens in the colon, and later as a normal tissue antigen in the fetal and adult digestive tract." (PMID 30314283, 2018). "CEACAM5 overproduction enriched for an epithelial gene expression pattern and facilitated tumor outgrowth at metastatic sites." (PMID 29736411, 2018). "Overexpression of CEACAM5 led to increased tumor growth in lungs, decreased expression of vimentin at the protein level, and decreased phosphorylation of p38." (PMID 29736411, 2018). "In conclusion, both CEACAM5 and αvβ6 are promising candidates for tumor-specific molecular imaging for PDAC." (PMID 28915633, 2017). "In univariate analyses, CEACAM1, CEACAM5 and CEACAM6 expression showed significant association with primary tumor site, while EPHA2 expression was associated with both lymphatic and venous invasion." (PMID 29262644, 2017). "The in vivo anti-tumour activity of anti-CEACAM5 CAR T cells further supported a strategy of targeting CEACAM5 within the context of a clinical trial." (PMID 28660319, 2017). "This study implies that molecular imaging using tumor-specific targets, such as αvβ6 and CEACAM5, can help to guide this process." (PMID 28915633, 2017). "Subsequently, multi-marker RT-PCR analysis was used to detect tumor-associated transcripts, including KRT19, MUC1, EpCAM, CEACAM5, and BIRC5." (PMID 28626429, 2017). "Avβ6 and CEACAM5 expression identified tumor-positive lymph nodes correctly in 84% and 68%, respectively, and in 100% of tumor-negative nodes for both biomarkers." (PMID 28915633, 2017). "Biomarkers αvβ6 and CEACAM5 met most of the criteria of an optimal tumor-specific biomarker and were selected for further evaluation." (PMID 28915633, 2017). "The 5G2 signal was also more predominant on the apical membrane and inside the lumen in patient tumours similar to CTOSs-derived xenotumours compared to the CEACAM5 and CEACAM6 signal." (PMID 27098764, 2016). "CEACAM5 is an adhesion molecule that was shown to be involved in cell adhesion, migration, anoikis, tumor invasion and metastasis." (PMID 26673628, 2015). "The carcinoembryonic antigen CEACAM5 is part of the immunoglobulin superfamily, which is perhaps best known as a tumour marker." (PMID 25970613, 2015). "CEACAM5 is overexpressed in several tumor types of epithelial origin and is known as an important and extensively used clinical tumor marker for colorectal and other carcinomas." (PMID 22738781, 2012). "These efforts were based on the fact that carcinoembryonic antigen had been previously proposed as tumor marker in several canine immunohistochemical studies using anti-human CEACAM5 antibodies such as Col-1." (PMID 21436956, 2011).
tumor (continued). "Though there is a strong correlation between CEACAM5 expression levels and tumor growth, little is known about its role in promoting proliferation." (PMID 21731662, 2011). "The availability of natural anti-CEACAM5 mAbs with significant tumor-targeting and -suppressing activity is still limited." (PMID 21731662, 2011). "An important example for a potential immunological cancer target is carcinoembryonic antigen (CEACAM5), which represents a classical tumor marker and is routinely exploited for diagnosis in man." (PMID 21436956, 2011). "Since resistance to anoikis is a characteristic of tumor cells, inhibition of anoikis by CEACAM5 suggests its role in facilitating tumorigenesis and metastasis." (PMID 21731662, 2011). "CEACAM5 and CEACAM6 are two tumor-associated antigens that play important regulatory roles in cell adhesion and in tumor cell chemosensitivity." (PMID 17201906, 2007). "For all tumors, the amount of CEACAM6 expressed was greater than that of CEACAM5, and reflected tumor histotype." (PMID 17201906, 2007). "Although CEACAM5 was subsequently found in normal tissues, its consistent overexpression in many cancers has made it a tumour marker widely used for patient management and a popular molecular target for novel cancer therapies." (PMID 17576469, 2007). "It is important to mention that the CHO-k1 cell lines express high levels of CEACAM5 compared to tumor cell lines and that saturation of the reporter cell line activity with CHO-k1-huCEACAM5 clone 11 might have been reached." (PMID 41283511, 2025). "Interestingly, in vitro MFE23-4-1BBL and Sm9b-4-1BBL (targeting membrane-distal CEACAM5 epitopes) performed superiorly in binding to tumor cells and in the functional Jurkat-human-4-1BB-NFkB-luc2 reporter cell assay." (PMID 41283511, 2025). "Specifically, in the group undergoing perioperative chemotherapy, there was a significant difference in CEACAM5 expression between tumor tissue and HM (p < 0.01), but this difference was even more significant in patients who did not receive perioperative chemotherapy (p < 0.001)." (PMID 40868067, 2025). "In addition, the analysis of CEACAM5 expression in patients stratified by TNM stage revealed a progressive increase in CEACAM5 levels corresponding to advancing tumor stage." (PMID 40868067, 2025). "Using IHC, CLDN4 and CEACAM5 were then evaluated on tumor and healthy tissue sections prepared from paraffin-embedded samples collected from patients who underwent a partial gastrectomy at the Digestive System Surgery Unit, AOU Careggi, Florence (respectively)." (PMID 40868067, 2025). "Additionally, we further explored the spatial transcriptomics data by performing spatial colocalization analysis between the CD8+ T cell marker gene (GZMB), the macrophage marker gene (CD68) and the tumour cell marker gene (CEACAM5)." (PMID 40770837, 2025). "The discrepancy between affinity determined by surface plasmon resonance and cell binding is likely caused by a different epitope accessibility on cells and/or differences in the glycosylation profiles between recombinant NABA-CEACAM5 and CEACAM5 expressed on tumor cell surfaces." (PMID 41283511, 2025). "Interestingly, a consistent methylation pattern was noted in normal tissue in contrast to the divergence in the corresponding tumor part with lower methylation in the CEACAM5 promoter." (PMID 37942534, 2024). "Both the intrinsic and extrinsic mechanisms of anoikis can be inhibited by CEACAM-5 which may result in the emergence of a secondary tumor." (PMID 39839775, 2024). "CEACAM5 is thereby widely used as a broad-spectrum tumor marker." (PMID 38275310, 2024). "Furthermore, DNA methylation profiling based on the NGS analysis of 156 patients indicated that the methylation difference in matched normal‐tumor pairs was located in regions −200 to −500 and −1000 to −1400 bp on the CEACAM5 promoter." (PMID 37942534, 2024).
tumor (continued). "In contrast, the high-affinity binding mediated by the anti-CEACAM5 arm induces the co-engagement of CD47 resulting in a “guided inhibition” of the CD47-SIRPα interaction between CD47 on CEACAM5-positive tumor cells and SIRPα on e.g., macrophages and natural killer cells." (PMID 38720892, 2024). "We next checked for differences in CEACAM5 gene expression between different tumor stages." (PMID 38730739, 2024). "To verify protein expression of CEACAM5 in human tissues, we performed IHC analysis with 14 different human tumor and 14 correspondent normal tissues (brain, breast, colon, muscle, kidney, liver, lung, pancreas, prostate, skin, small intestine, stomach, ovary, and uterus) on the tissue microarray." (PMID 36923424, 2023). "Interestingly, CEACAM6 expression was higher than traditional biomarker CEACAM5 (CEA) in CSF tumor cells." (PMID 36082960, 2023). "Furthermore, it has also been shown that NEO-201 can block the interaction between CEACAM-5 expressed on tumor cells and CEACAM-1 expressed on NK cells to reverse CEACAM-1-dependent inhibition of NK cytotoxicity." (PMID 36991390, 2023). "Simultaneous binding of NILK-2301 to CEACAM5-positive tumor cells and CD3ε-expressing T-cells leads to T-cell activation, proliferation, and secretion of cytokines and cytotoxic enzymes, ultimately leading to tumor cell killing." (PMID 38087365, 2023). "Anti-CEA/CEACAM5 mAb was used to identify the tumor cells in the tissue sections." (PMID 38156105, 2023). "This trial was designed with two cohorts based on CEACAM5 expression levels by immunochemistry ≥2+ in moderate expressors (intensity between ≥1% to <50% of tumor cell population) and high expressors (≥50% of the tumor cell population)." (PMID 38067208, 2023). "Moreover, CEACAM5/6+ ductal cells (clusters 2/3) were the predominant subclusters in the S5 state, and only emerged at the latest stage in tumor tissues, demonstrating their highly malignant properties." (PMID 37612267, 2023). "Thus, elevated levels of soluble CEACAM1 as well as membrane-anchored or soluble CEACAM5 proteins can modify immune response, angiogenesis and properties of epithelial cells favoring tumor-appropriated environment." (PMID 37691945, 2023). "We sought further insights into the tumor growth inhibition activity of anti-CEACAM5 CAR-T and ADC SAR408701 analog by examining their activity in a CEACAM5-negative DM4S A549 tumor model, because the ADC SAR408701 analog showed a CEACAM5-independent killing activity in vitro cell-based system." (PMID 36923424, 2023). "Here, we designed a model system using cell lines derived from NSCLC tumors, which are resistant to DM4 or an in-house developed analog of SAR408701, and our anti-CEACAM5 CAR-T cells showed CEACAM5-specific anti-tumor activities for DM4-resistant NSCLCs in vitro and in vivo." (PMID 36923424, 2023). "Moreover, tumor clusters had higher expression levels of tumor makers, including LAMC2, MSLN, TFF2, and CEACAM5, compared with ductal clusters, which further verified their tumor identity." (PMID 36944944, 2023). "Tusamitamab-ravtansine is an ADC that selectively targets CEACAM5-expressing tumor cells." (PMID 38067208, 2023). "To confirm that NEO-201 binds specifically to cancer cells expressing tumor-associated variants of CEACAM-5 and CEACAM-6, which are not expressed in normal tissues, we used human tissue microarrays of various cancer types for immunohistochemistry analysis." (PMID 35804808, 2022). "NEO-201 can also indirectly enhance anti-cancer activity through the blockade of the interaction between CEACAM-5 expressed on tumor cells and CEACAM-1 expressed on natural killer cells to reverse CEACAM-1-dependent inhibition of NK cytotoxicity or through its binding to human regulatory T cells." (PMID 35804808, 2022). "In 1965, CEA (more currently known as CEACAM5) was first identified as a tumor marker for CRC." (PMID 35115044, 2022). "CEACAM5 was recognized as a tumor biomarker and an indicator of cancer recurrence." (PMID 36568638, 2022).
tumor (continued). "The discovery of the inhibitory role of CEACAM5+ tumour cells in the innate immune cells increases emphasis on harnessing innate immunity in immunotherapy, particularly when most of the current immunomodulatory approaches have focused on unleashing effector T cells." (PMID 36494785, 2022). "In previous studies, we reported that the humanized IgG1 mAb NEO-201 reacts against numerous carcinomas expressing tumor-associated variants of CEACAM5 and CEACAM6, but it is not reactive against most normal epithelial tissues." (PMID 36291783, 2022). "Previously, we reported that NEO-201 binds to several tumors expressing tumor-associated CEACAM5 and CEACAM6 variants but does not bind to those expressed in healthy tissues." (PMID 36291783, 2022). "The free interstitial concentration in the tumour was slightly higher than the total tumour concentration for cibisatamab while the opposite was observed for CEACAM5-TCB, which might be due to the higher CEA binding affinity of CEACAM5-TCB." (PMID 34959386, 2021). "Although a humoral response against the transcription factor Ascl2 was not expected, our results demonstrate the capacity of our vaccine platform to promote a strong humoral response, which is of great interest for developing vaccines against tumor surface antigens, such as Epcam or CEACAM5." (PMID 33671373, 2021). "A biodistribution study was performed in humanised NSG mice after intravenous (i.v.)injection of either cibisatamab or CEACAM5-TCB in order to investigate the distribution of the two TCBs into the tumour interstitial space and their accumulation therein due to target binding." (PMID 34959386, 2021). "As has been found for other markers, a notable discordance in expression of CEACAM5 between primary tumor and metastasis may have implications for choosing treatment strategies after surgical removal of the primary tumor." (PMID 33196697, 2020). "Integrin αvβ6 and CEACAM5 detect primary tumors and tumor positive lymph nodes." (PMID 33004930, 2020). "It is possible that a difference in glycosylation pattern explains the specific binding of NEO-201 to specific tumor-associated CEACAM-5 and CEACAM-6 variants but not to those expressed on healthy tissues as shown by the immunohistochemistry analysis." (PMID 32637350, 2020). "The importance of CEACAM5 in tumor cells disseminating to lymph nodes and to more distant sites like lung tissue may even differ." (PMID 33196697, 2020). "Furthermore, a more favorable prognostic effect of high levels of CEACAM5 was observed in some sub-clusters of the TN tumor subtype, including Basal-like 1 and Luminal androgen receptor subsets of tumors." (PMID 33196697, 2020). "Integrin αvβ6, CEACAM5, and mesothelin demonstrated membrane-bound tumor cell expression." (PMID 33004930, 2020). "The Ehi cells highly express oncogenic cell–cell adhesion molecules, such as carcinoembryonic antigen-related cell adhesion molecule 5 (CEACAM5) and CEACAM6 that associate with E-cadherin, resulting in increased tumor cell cluster formation and metastatic seeding." (PMID 31331982, 2019). "Besides its pro-metastatic function, CEACAM5 in the blood stream can trap anti-CEACAM5 antibodies and thereby impede the direct targeting of the tumor." (PMID 31447859, 2019). "Furthermore, only CEACAM5 expression in PDAC was slightly more intense in the invasive border compared to the tumor core." (PMID 28915633, 2017). "The fact that CEACAM5 could be a potential biomarker for the tumor-specific identification of PDAC would lead to other advantages." (PMID 28915633, 2017). "The tumour-associated antigen explored in this trial was carcinoembryonic antigen (CEA; CEACAM5; CD66e) which is expressed at high levels in a broad range of tumours including those of the gastrointestinal tract and has been extensively explored as a cancer vaccine target." (PMID 28660319, 2017).
tumor (continued). "Two potential explanations for this effect could be: (i) there is tumor heterogeneity where the subtype with CEACAM5 expression is selectively killed by the (radio)chemotherapy, or (ii) the neoadjuvant therapy has a selective effect on the cell genome." (PMID 28915633, 2017). "In squamous carcinoma of tongue, CEACAM5 expression with cytoplasmic staining is different from normal tongue tissue with membranous staining, and the transformation of CEACAM5 distribution from membrane to cytoplasm is an important incident for the invasion and differentiation of tumor." (PMID 22738781, 2012). "Hence, CEACAM5 is an attractive target for immunotherapeutic purposes because of its expression profile, its role in tumor progression, and its immunogenicity." (PMID 22738781, 2012). "A humanized anti-CEACAM5 mAb, labetuzumab, and human monoclonal antibodies (HmAbs) were found able to suppress tumor growth and metastasis, while other mAbs labeled with radioactive isotopes were applied for tumor imaging." (PMID 21731662, 2011). "Nevertheless, because of their ectopic or deregulated overexpression in up to 70% of all tumours, CEACAM5 and CEACAM6 represent popular targets for novel cancer therapies, including cancer vaccines, cellular immunotherapy, radioimmunotherapy, and antibody therapy." (PMID 17576469, 2007). "Finally, we assessed the diagnostic performance of TFF2 alongside conventional tumor markers, including CEA (CEACAM5) and CA125 (MUC16), for PanIN and PC through ROC curve analysis, and the AUC values were 1.000 and 0.904, significantly outperforming other tumor markers." (PMID 41040532, 2025). "Furthermore, in comparison with healthy tissue, the tumor samples labeled with a CMG antibody displayed a distinct membrane-associated signal, comparable to that observed with the commercial anti-CEACAM5 antibody that lacks NIR conjugation." (PMID 40868067, 2025). "However, in MKN45 and HPAFII in vivo xenograft models in humanized NSG mice, the CEA-4-1BBL antibody fusion protein constructed with the CEACAM5 antibody T84.66-LCHA targeting a membrane-proximal CEACAM5 epitope showed the best tumor control overall in combination with CEA-TCB." (PMID 41283511, 2025). "Nevertheless, a minority of patients show high CEACAM5 gene expression also in the higher stages, although not represented in our protein staining assay, which might confine anti-CEACAM5 treatment exclusively to patients with prior CEACAM5 staining of their tumor tissue." (PMID 38730739, 2024). "Neither CEACAM5 nor CEACAM6 have previously been linked to resistance to tumor acidity." (PMID 38502695, 2024). "Consequently, the cytotoxicity against tumor cells is twofold, both directed toward CEACAM5-expressing tumor cells and enhanced through the bystander effect (the potential release of the cytotoxic component into the extracellular space, with subsequent bystander cell death)." (PMID 38001628, 2023). "To characterize the heterogeneity of TROP2, DLL3, and CEACAM5 expression, we quantified the hypergeometric probability of concordant binarized H-scores (both ≥20 or both <20) for random pairs of samples from a given patient (intra-patient, inter-tumoral) or from the same tumor (intra-tumoral)." (PMID 38196594, 2023). "In addition, 2 of the 3 patients with a partial response in the main Q2W dose-escalation cohort had strong expression of CEACAM5 (intensity ≥2+ in 100% of tumor cells), whereas 17 of 43 (40%) patients in the current study had CEACAM5 expression of intensity ≥2+ in ≥80% of tumor cells." (PMID 37645622, 2023). "In addition, IHC analysis of different human tumor tissues confirmed that NEO-201 binds specifically to tumor cells expressing a tumor-associated variant of CEACAM-5 and CEACAM-6, while it does not react against healthy tissue." (PMID 35804808, 2022).